HLA-E (major histocompatibility complex, class I, E)
Diseases named in the same sentence as HLA-E in open-access papers (continued):
Sharing a sentence is not in itself a finding about the gene and the disease.
tumor (continued). "In CTCL, our findings show that all three classical MHC-I proteins (HLA-A, HLA-B, and HLA-C), but not the non-classical MHC-I (HLA-E), exhibit high expression levels on tumor T cells from MF skin lesions." (PMID 38272918, 2024). "Unlike its role in healthy tissues, HLA-E in tumor tissues significantly regulates the high reactivity of NKG2A + Vδ2 TILs, ultimately generating dysfunctional immune cells and tumor cell escape." (PMID 36793048, 2023). "Since overexpressed HLA-E can prevent tumor cell lysis mediated by Vδ2 T cells, the blockade of the NKG2A-HLA-E axis may enhance the Vδ2 T cell-based immunotherapeutic efficacy by administering anti-NKG2A/CD94 mAb to unleash Vδ2 T effector functions." (PMID 36831606, 2023). "Histocompatibility leucocyte antigen E (HLA-E) and its cognate inhibitory receptor NKG2A could serve as a novel immune checkpoint to be targeted for inducing anti-tumor immunity." (PMID 36816030, 2023). "Hence, down-regulation of NKG2A on NK cells increases antitumor activity against HLA-E expressing resistant tumor cells and blocking NKG2A in combination with the PD-1/PD-L1 pathway improves tumor control." (PMID 37936122, 2023). "Being a member of class Ib non-classical human leukocyte antigens (HLA) molecules, HLA-E is expressed constitutively on B and T lymphocytes, NK cells, monocytes, trophoblasts, and also in tumour cells." (PMID 36899273, 2023). "More interestingly, not all tumor cell lines overexpressed HLA-E, even without HLA-E expression, which is inconsistence of cancer tissues." (PMID 38007483, 2023). "Further characterization of our screening and transcriptional data implicated Qa-1b (encoded by H2-T23), the murine homolog of Human leukocyte antigen E (HLA-E) and a downstream target of IFNγR/JAK/STAT signaling, in promoting tumor cell resistance to CAR-T therapy." (PMID 38052854, 2023). "Therefore, the aim of this study was to retrospectively analyze HLA-E expression in OSCC patients and the impact on tumor progression and survival in a large cohort of patients (n = 222)." (PMID 38069020, 2023). "Various mechanisms can be involved, including upregulation of inhibitory ligands and non-classical MHC class I molecules HLA-E and HLA-G on the tumour that suppress NK cell cytotoxicity and induce tumour tolerance." (PMID 35806034, 2022). "TFL-033 binding to HLA-E may prevent interaction with receptors (CD94/NKG2a) of NK cells and promote tumor cytotoxicity." (PMID 35214796, 2022). "MHC class I antigen E (HLA-E), a ligand for the inhibitory NKG2A/CD94 receptor of the immune system, is responsible for evading the immune surveillance in several settings, including senescent cell accumulation and tumor persistence." (PMID 35991867, 2022). "The expression levels of B2M(p = 2.926e-05), HLA-C(p = 2.628e-03), HLA-E(p = 5.5166e-08), HLA-F(p = 9.376e-03), TAP1(p = 1.972e-09), TAP2(p = 1.245e-04) and TAPBP (p = 2.652e-12)in tumor tissues of dMMR patients were significantly higher than those of pMMR patients." (PMID 36527024, 2022). "However, in the tumor context of CRC, over-expressed HLA-E is an immune escape mechanism that inhibits NK cell activation through high-affinity interaction with the NKG2A receptor." (PMID 36686835, 2022). "The non-polymorphic nature of HLA-E, and the high surface expression of HLA-E on tumour cells compared to healthy tissue makes it an attractive target." (PMID 36560403, 2022). "Recent studies revealed that a majority of tumor‐infiltrated NK cells and CD8+ T cells express the NKG2A receptor that transmits the inhibitory signal to inhibit the function of NK and CD8+ T cells upon binding with HLA‐E in human or Qa‐1b ligand in mice." (PMID 37693065, 2022). "For instance, HLA-G and HLA-E, the non-classical MHC-I molecules implicated in the protective maternal-fetal barrier in the placenta, are highly upregulated on tumor and myeloid cells in the EwS TME." (PMID 36612267, 2022).
tumor (continued). "Comparisons of immune cell infiltrates in HLA-E positive and negative EwS tumor samples through multicolor immunofluorescence staining did not reveal significant associations of HLA-E expression with higher densities of infiltrating myeloid cells or T cells." (PMID 34201079, 2021). "In this model, the contemporary targeting of NKG2D ligands MICA/B on tumor cells, and the inhibitory receptor NKG2A on NK cells, led to a synergistic effect in blocking tumor cell growth, even if it expressed the NKG2A ligand HLA-E." (PMID 34298630, 2021). "According to the expression profile of HLA-E/β2m, the therapeutic response at 3 months was not statistically different between the 2 groups of tumors HLA-E+vs HLA-E−, regardless of the tumor site considered, primary or paired metastatic." (PMID 34211852, 2021). "In cancer, no tumor-derived peptides with binding specificity for HLA-E have been identified to date." (PMID 34446788, 2021). "The ligand for these receptors is the non-classical HLA-E molecule, frequently overexpressed in different types of tumor cells." (PMID 33919155, 2021). "However, the expression of the NK cell inhibitory ligand HLA-E exhibited the opposite pattern, with lower expression in MDA-MB-231 tumor tissue than in RT-R-MDA-MB-231 or CD24−/low/CD44+ tumor tissue." (PMID 34502547, 2021). "HLA-E, an inhibitory ligand signaling via CD94/NKG2A, was found to be decreased upon selenite-induced oxidative stress and facilitated the enhanced NK-cell-mediated killing of tumor cells." (PMID 33265951, 2020). "Moreover, a direct correlation between levels of HLA-E expression and those of NKG2A and CD94 in tumor-infiltrating lymphocytes has been observed." (PMID 33255582, 2020). "The interaction between NKG2A and HLA-E is thought to block the cytotoxic activity of CD8+ T cells and NK cells and a couple of studies have shown that expression of HLA-E by tumor cells restrained the prognostic impact of tumor-infiltrating CD8+ T cells, including that of HPV16+ OPSCC." (PMID 33425717, 2020). "HLA-E is a nonclassical MHC I that is expressed on tumor cells and binds to NK cells receptors such as CD94/NKG2A, CD94/NKGK2B and CD94/NKG2C." (PMID 32784928, 2020). "HLA-E molecules are expressed by many tumor cells, however, the expression of HLA-E molecules on endometriotic cells has not been confirmed as yet." (PMID 31540116, 2019). "Tumor cells did not express HLA-E in control spheroids but its expression was strongly induced by the presence of immune cells." (PMID 30871626, 2019). "On principle, we postulate that NK cell passive immunotherapy should capitalize on both of these features of monospecific HLA-E mAbs, that is, the specific determination HLA-E expression on a particular tumor and the enhancement of NK cell/CD8+ cytotoxicity if HLA-E positive." (PMID 31009335, 2019). "Non-classical MHC class Ib molecules, e.g., HLA-E, HLA-F and HLA-G, are known to promote tumor escape from CTL and NK cell immune surveillance by binding to their inhibitory receptors." (PMID 29283429, 2017). "Interestingly, we also assessed tumor cell expression of HLA-E and NK cell expression of NKG2A as HLA-E is a known ligand for the NK cell inhibitory receptor NKG2A." (PMID 27314237, 2016). "Next to this it was investigated whether a correlation between HLA-E expression in RCC lesions and WHO tumor grading exists, which was statistically significant for HLA-G as recently reported." (PMID 27589686, 2016). "The expression of HLA-E by tumor cells was an independent negative prognostic factor for OS (p=0.031)." (PMID 26658106, 2016). "Classic human leukocyte antigen-I (HLA-Ia) molecules are reduced or absent on the surface of tumor cells, whereas non-classic HLA (HLA-Ib) molecules, such as HLA-G and HLA-E, are highly expressed on the surface of tumor cells." (PMID 27322426, 2016). "In our study, a high expression of HLA-E by tumor cells clearly had a negative effect on CD8+ T cells." (PMID 26658106, 2016).
tumor (continued). "The non-classical human leukocyte antigen E (HLA-E) expression is frequently overexpressed in tumor diseases, transplants and virus-infected cells and represents an immunomodulatory molecule by binding to the receptors CD94/NKG2A, -B and –C on NK and T cells." (PMID 27589686, 2016). "Tumor tissue of 197 patients with resected pulmonary adenocarcinoma was analyzed for the presence of CD8+ T cells and the expression of β2-microglobulin, HLA-A, HLA-B/C and HLA-E." (PMID 26658106, 2016). "The metastatic tumor cells showed less expression of HLA-E (26 %) and HLA-G (28 %), however, this was not significant." (PMID 27895918, 2016). "Despite LAK cells showed an enhanced lysis capability, the cytotoxicity was not reduced in the presence of HLA-E-overexpressing tumor cells." (PMID 27589686, 2016). "We speculated HLA-E induced expression of IL-10 and TGF-β by NK cells via these indirect mechanisms in the tumor-NK cell interaction in vivo." (PMID 27322426, 2016). "CD8+ T cell infiltration strongly contributes to a better prognosis in NSCLC when the tumor cells retain the expression of classical HLA class I and do not express HLA-E." (PMID 26658106, 2016). "Sections of this TMA were immunohistochemically stained and quantified for presence of Foxp3+ cells (Tregs) and tumor expression of HLA Class I and non-classical HLA-E and HLA-G." (PMID 24997850, 2014). "Despite the downregulation of HLA class I molecules during the tumor immune escape, the surface expression of HLA-E is not affected." (PMID 25401109, 2014). "For HLA-E, 8 patients (1.6%) showed absence of tumor staining, 73 patients (15.0%) showed weak tumor staining, 298 patients (61.3%) showed moderate tumor staining and 107 patients (22.0%) showed strong tumor staining in their punches." (PMID 24997850, 2014). "In contrast, cells with low to absent HLA-class I expression (i.e., tumor cells and virus-infected cells) generate low amounts of HLA-derived peptides, and consequently their surface expression of HLA-E is low." (PMID 24741633, 2014). "We found that overall HLA-E expression is a significant prognosticator, and in combination with HLA-A expression and the presence of NKG2A infiltrating lymphoid cells provides a clue to understand tumor immune surveillance in vivo." (PMID 22032294, 2011). "Thus, tumour cells often downregulate classical HLA-I molecules whilst upregulating the expression of non-classical HLA-I molecules, especially HLA-E, to evade both T cell and NK cell surveillance." (PMID 40361496, 2025). "Cell-cell communication is significantly higher in tumor tissues than in normal tissues, which is critical for tumor formation and therapy resistance.HLA-E, a non-classical class I MHC molecule, is typically expressed at low levels in most human tissues but shows significant upregulation in HCC." (PMID 40534863, 2025). "Furthermore, antigen-presenting molecules and immune molecular interactions, such as those between HLA-A, HLA-B, HLA-C, HLA-E, and HLA-F with CD8A and CD8B, appeared to be significantly up-regulated in tumor tissues, while their presence in normal tissues was comparatively diminished." (PMID 40723292, 2025). "In addition, tumour cells can increase the expression of non-classical HLA class I molecules, such as HLA-E and HLA-G." (PMID 40639721, 2025). "Importantly, it has recently been shown that circulating tumour cells are protected from NK-cell mediated clearance via NKG2A:HLA-E interactions, with HLA-E expression promoted by platelet-derived RGS18 and NKG2A blockade able to restore NK function and prevent tumour metastasis in vivo." (PMID 38223411, 2024). "In addition to avoid from activating NK receptors, tumor cells can upregulate the expression of inhibitory ligands, such as HLA‐G (ligand for KIR), HLA‐E (ligand for NKG2A/CD94), or PD‐L1, which engage inhibitory receptors on NK cells, resulting in the inhibition of NK cell cytotoxicity." (PMID 38882209, 2024).
tumor (continued). "However, HLA-E expression in tumor microenvironment (TME) does not also always depend on the expression of HLA-A, B and C alleles." (PMID 39229258, 2024). "For instance, in cancers marked by the overexpression of non-classical HLAs, like HLA-G or HLA-E, interventions aimed at blocking their interactions with immune receptors could potentially restore immune surveillance and amplify anti-tumor responses." (PMID 39766165, 2024). "The high NKG2A expression level in NK and CD8+ T cell subsets in the tumor microenvironment in OC, together with the high response rate in NKG2A+ traNK cells that we detected in this study, suggest that blocking the NKG2A – HLA-E interaction may be beneficial for patients with OC." (PMID 37444472, 2023). "Thus, the effect of IFNγ on tumor cell response to CAR-T therapy will not only depend on context and timing but also the ability of tumors cells to induce inhibitory receptors like HLA-E in response to inflammatory signals, as well as their general sensitivity to IFNγ-mediated death." (PMID 38052854, 2023). "In addition, NKG2A+ Vδ2 T cells present higher cytotoxic potential against HLA class I deficient tumor cell targets that do not express the NKG2A ligand, HLA-E." (PMID 36831606, 2023). "However, educated NK cells are inhibited by the aberrant expression of HLA-E on HCC cells, resulting in an inhibitory function on Vδ2pos T cells, which are also unable to perform ADCC and escape immunological surveillance by the tumor." (PMID 37371767, 2023). "Furthermore, the differences in the anti-tumor potential of NKG2A+ and NKG2A− Vδ2 T provide functional indications of their potential uses and indicate the optimal choice according to the immunosuppressive HLA-E-mediated TME." (PMID 36831606, 2023). "Furthermore, NKG2A, but not NKG2C, was also upregulated on NK cells in tumor tissue from patients with HCC compared to patients without HCC, and higher NKG2A expression was associated with increased HLA-E expression." (PMID 37371767, 2023). "Interestingly, this population of cells may also be involved in tumor antigen presentation, since genes for MHC-I molecules (HLA-A, HLA-B, HLA-C, HLA-E, and HLA-F) were highly expressed in this cluster." (PMID 37533434, 2023). "Its immunosuppressive effect is exerted from the interaction between NKG2A/CD94 and the non-classical HLA class I histocompatibility antigen, alpha chain E-(HLA-E) molecule overexpressed in these tumours, inhibiting the effector functions of CD8+ T and NK cells after phosphatase SHP-1 recruitment." (PMID 36140252, 2022). "Moreover, the majority of PDS showed strong MHC-I expression and upregulated HLA class I molecules (HLA-A, HLA-B, HLA-C and HLA-E, corresponding in humans to the MHC class I) that are involved in tumor neoantigen presentation to tumor-specific CD8+ T lymphocytes leading to tumor cell apoptosis." (PMID 36465341, 2022). "HLA-E is a non-classical MHC class I molecule expressed by different cells including tumor cells." (PMID 35267497, 2022). "However, HLA-E expressed by EwS tumor cells or by myeloid bystander cells both failed to reduce antitumor effector functions of CART." (PMID 34201079, 2021). "In addition to NK cells, inhibition of NKG2A has also been shown to enhance the efficacy of cancer vaccines in murine tumor models via CD8+ T cell activation and therefore selinexor mediated HLA-E downregulation may also promote T cell activity." (PMID 34926302, 2021). "Thus, HLA-E does not impair the cytolytic capacity of tumor-antigen-specific CART in direct interactions with EwS cells." (PMID 34201079, 2021). "We found positive staining of tumor cells in IHC staining for VISTA in 2.1% (3/145), Galectin-9 in 36.6% (53/145), PD-L1 in 40.7% (59/145), CEACAM-1 in 57.2% (83/145), HVEM in 74.5% (108/145), PVR in 77.9% (113/145) and HLA-E in 84.8% (123/145) of patients 29–33." (PMID 34135436, 2021).
tumor (continued). "One possibility to explain the beneficial effect of high HLA-E expression and NK cell is that an increase in HLA-E may saturate NKG2A, thus shifting the interaction toward NKG2C and away from NK inhibition to promote tumor lysis." (PMID 34426671, 2021). "Specific AdCAR-mediated cytotoxicity could be demonstrated regardless of tumor cell surface expression of inhibitory ligands such as HLA-E which was shown to have negative effects cytotoxic activity of primary NK cells." (PMID 33807875, 2021). "Furthermore, western blot showed that inhibition of AKT1 reversed the effect of si-ATF3 to significantly increase Fas protein expression in tumor tissues, while to significantly decrease HLA-A, CCR5, FasL, HLA-E protein expression, which implied that the immune escape of cancer cells was diminished." (PMID 33794833, 2021). "Although OC-infiltrating NK cells' NKG2A expression has not been expressly measured, the abundance of HLA-E on OC tumors would suggest that preventing inhibition of NK cells via NKG2A may enable strong anti-tumor reactivity." (PMID 31456796, 2019). "Different levels of HLA-E expression were observed, which could be further induced after IFNγ treatment, suggesting that HLA-G has no role in a tumor’s escape from the immune system, while HLA-E should be further investigated." (PMID 31394860, 2019). "Therefore, we hypothesize that HLA-E is highly expressed in NB tissue, inhibits NK cells, and promotes the release of IL-10 and TGF-β1 to affect tumor growth." (PMID 27322426, 2016). "In conclusion, our results confirm the pivotal protective role of tumor infiltrating CD8+ T cells in NSCLC and in addition show that their effect is particularly apparent when the tumor cells retain the expression of classical HLA class I and do not express the non-classical molecule HLA-E." (PMID 26658106, 2016). "The natural ligand of CD94/NKG2A is HLA-E, a non-classical HLA class I molecule that is expressed on the cell surface of most leukocytes and on transformed cells, including virus-infected cells and tumor cells." (PMID 26697006, 2015). "HLA-E-mediated tumor resistance might at least partly explain the negative clinical trail results obtained so far." (PMID 25920521, 2015). "Similarly, stratifications of the EBV-positive cHL series by histology and other clinical parameters (disease stage, presence of bulky tumor and survival) did not reveal any differences in the distribution of the HLA-E genotypes (data not shown)." (PMID 26261988, 2015). "Thus, HLA-E may collaborate with HLA-G in the protection of TAM from NK cell lysis and in the establishment of a tolerogenic tumor microenvironment." (PMID 25202308, 2014). "This challenges the pre-existing notion that tumours such as OC evade immune recognition primarily through MHC downregulation and instead suggests that OC may maintain antigen presentation and rely more heavily on immunosuppressive techniques (via HLA-E) as a key strategy of immune evasion." (PMID 41463341, 2025). "Therefore, solely evaluating the HLA-E expression in tumor cells may not be sufficient; understanding its presence within the tumor microenvironment (TME) provides more compelling evidence." (PMID 39845968, 2024). "Moreover, and different than MHC class Ia molecules, HLA-E is resistant to HIV Nef-mediated downregulation, rendering HLA-E a good candidate as an antigen-presenting molecule for the formulation of a peptide-based subunit vaccine for immunotherapy in infectious diseases or tumour immunology." (PMID 38106407, 2023). "In 10 (31.3%) tumor patients no HLA-E could be detected in the serum." (PMID 38069020, 2023). "We also found TNF-α could upregulate HLA-E protein expression in tumor cells (data was not shown)." (PMID 38007483, 2023).